CD22 (CD22 molecule)
Diseases named in the same sentence as CD22 in open-access papers (continued):
Sharing a sentence is not in itself a finding about the gene and the disease.
leukemia (continued). "This design adds another tool to the arsenal against CD22+ leukemias and may also provide an alternate, complementary approach to the treatment." (PMID 37269947, 2023). "Dendritic cells sometimes expressed CD22 in rare cases of leukemia, which may contribute to the higher incidence of carHLH in trials of CD22 CAR-T therapies, but the correlation and further mechanism need more studies in the future." (PMID 37864230, 2023). "Moreover, increasing the affinity of m971 scFv did not improve in vitro and in vivo CAR-T cell activity against CD22-low leukemia cells." (PMID 37821931, 2023). "Engineered CAR T cells specific for CD22 or CD123 showed similar antitumor activity toward their respective leukemia cell line targets (RAJI and MOLM13 tumor cells, respectively) regardless of the number of edited features (ΔTRACCAR, ΔTRACCARΔB2M, and ΔTRACCARΔB2MHLAE)." (PMID 35773273, 2022). "We show that exposing leukemia cell lines to anti-CD22 CAR-T also changes CD22 surface expression." (PMID 35222407, 2022). "In addition, the humanized anti-CD22 CAR- T cells exhibits potent activity against leukemia cells with low CD22 expression." (PMID 35757715, 2022). "Meanwhile, CD22 retains its expression on the surface of leukemia cells." (PMID 33898316, 2021). "Therefore, being able to quickly change the therapeutic target such as CD19 or CD22 is important for the leukemia resistant treatment." (PMID 33422061, 2021). "In clinical studies using CD22-redirected CAR T cells to treat ALL, leukemia escape was caused by emergence of leukemia variants with low-level CD22 expression in the absence of mutations, as observed with CD19." (PMID 32357417, 2020). "Furthermore, the recurrent leukemia cells remained sensitive to lysis by autologous CD19/CD22 CAR T cells." (PMID 32245502, 2020). "However, for CD19 targeted therapy, a sub-population of cancer cells in B-Lineage Leukemia patients turned to express CD22, thus escaped the killing mediated by CD19 targeted therapy." (PMID 32989604, 2020). "The investigators went further to show in animal studies that differential levels of CD22 on leukemia cells could have a dramatic impact on anti-cancer efficacy." (PMID 30915277, 2019). "Additionally, phase 1/2 trials of CAR T cells targeted against CD22 are underway, as well as preclinical work to identify other potential leukemia protein targets such as CRLF2, mixed lineage leukemia (MLL), and CD123." (PMID 30670684, 2019). "The median remission time, however, did not exceed 6 months, which could be largely traced back to the emergence of leukemia cells with reduced CD22 expression, eluding CD22-CAR T cells." (PMID 31195686, 2019). "To delve deeper into leukemia cell proliferation post-injection, we noted that the percentage of CD19 or CD22 positive peripheral blood (PB) cells following CD19-CD22 CAR-T treatment was markedly lower than in other groups." (PMID 40719826, 2025). "Both CD22 TCR-T and CD22 CAR-T cells eradicated leukemia in xenografts, but only CD22 CAR-T cells induced dose-dependent systemic inflammation." (PMID 40203088, 2025). "Cells with lymphoid markers were also present in the transcriptionally defined leukemia cells, but in smaller proportions, including CD19+/CD22+/CD30+ cells (5.96%) CD19+/CD22+/CD45+ cells (5.49%), CD3+/CD5+/CD7+ cells (4.45%), and CD3+/CD4+/CD5+ cells (0.4%)." (PMID 39294124, 2024). "Anti-CD22 CAR T cell trials for relapsed and refractory B cell ALL showing anti-leukemia responses have opened the door to using dual-targeting CAR-T cells." (PMID 38023730, 2023). "In a study with CD22 CAR-T cells for r/r B-ALL (ChiCTR-OIC-17013523), 24 of 30 patients achieved CR within 1 month, and the 12-month leukemia-free survival rate for patients was 71.6%, with most patients experiencing only minor adverse effects." (PMID 36261831, 2022). "Patient 2 relapsed 13 months after therapy with leukemia cells expressing both CD19 and CD22 antigens similar to pretreatment." (PMID 35317863, 2022).
leukemia (continued). "Other promising results have been obtained in the NCT03330691 clinical trial evaluating the safety and feasibility of CD19 and CD22 specific CAR-T cells in treating pediatric CD19- and CD22-positive leukemia." (PMID 36389658, 2022). "As expected, CD22 CAR-T induced profound and rapid down-regulation of CD22 antigen expression on the leukemia cell surface." (PMID 35222407, 2022). "When CAR-T cells specific for CD22 were analyzed for either CD22 or CD19 acquisition following co-culture with leukemia target cells, CD19 appeared to transfer more readily to the CAR-T cell surface than CD22." (PMID 35222407, 2022). "Diminished CD22 site density in the leukemic blasts, as determined by flow cytometry, was adequate to evade the infused CAR T cells, thus enabling leukemia relapse, and these results were consistent with those of the other clinical studies." (PMID 32245502, 2020). "We further demonstrate that select analogs potently increase cell surface expression of CD22, a promising CAR T cell target for the treatment of leukemias, highlighting the clinical potential of bryostatin analogs for enhancing targeted immunotherapies." (PMID 32312992, 2020). "For CD22 targeted therapy, HCL represents only a small portion of patients with leukemia and expanding the use of the drug to a wider population of patients is critical." (PMID 32989604, 2020). "CD19 and CD22 CAR T cells have demonstrated remarkable success in children with relapsed and refractory leukemia and lymphoma." (PMID 30459759, 2018). "Dozens of extracellular molecules are now being investigated for their value as tumor antigens and, in leukemia, these include CD19, CD20, CD22, CD30, Lewis Y antigen, among others." (PMID 26056592, 2014). "Alongside CD22, we extend our focus to CD33, another prominent Siglec member, which has been scrutinized for its pivotal role in hematological malignancies, especially leukemia." (PMID 38254780, 2024). "Additionally, for patients infused with CD19/CD22 CAR-T cells, Rituximab combined with CAR-T effectively improved the leukemia-free survival (LFS) of r/r B-ALL patients." (PMID 38662336, 2024). "Here, we demonstrate that newly diagnosed B-ALL patients with very low levels of residual wildtype CD22 (“CD22E12low”), as measured by RNAseq-based CD22E12 mRNA levels, have significantly worse leukemia-free survival (LFS) as well as overall survival (OS) than other B-ALL patients." (PMID 36900389, 2023). "No obvious leukemia-free survival advantage was found in patients who received tandem CD19/CD22 CAR T-cell therapy compared with those who received single CD19 or sequential CD19/CD22 CAR T-cell therapy." (PMID 37095120, 2023). "In our study, CD22/CD19 sequential therapy provided all 4 patients with a time window for allo-HSCT, but limited by economic or other reasons, only patient 1 received allo-HSCT and obtained long-term leukemia-free survival up to 1 year until recent follow-up." (PMID 35317863, 2022). "Moreover, it is now possible to detect antibodies present in leukemia cells, such as CD52, CD38, CD33, CD20, CD25, CD19, and CD22, and target them with new antibody–drug conjugates." (PMID 35011701, 2022). "However, the expression of CD22 in general is lower than CD19 and leukemia-free survival is significantly lower than in CD19-CAR-T cell therapy." (PMID 35456250, 2022). "The relapsed leukemia cells expressed the target CD19 and CD22 antigens at pretreatment levels." (PMID 32245502, 2020). "Notably, in vitro experiments indicate that relapsed leukemia cells retain CD19 expression and sensitivity to bispecific CD19/CD22 CAR T cells ex vivo." (PMID 32245502, 2020). "The SPDP-based immuno-RNases meditated a dose-dependent cytotoxicity towards targeted CD22-positive tumor cells but not towards the CD22-negative leukemia cells." (PMID 26605343, 2015).
leukemia (continued). "In multiply relapsed disease, patients may experience CD19low (several hundred molecules per cell) or negative leukemia, yet the expression level in most cases still exceeds the expression of CD22, an alternative CAR-targeted antigen." (PMID 35456250, 2022). "Similarly, in a Phase I trial of CD22 CAR T cells of children with ALL, after initially achieving a complete response, most patients relapsed with leukemia expressing lower levels of CD22 than their pre-treatment samples, apparently below the threshold for CAR efficacy." (PMID 30459759, 2018). "This may indicate that the increased killing of REH and NALM6 is not due to the increased number of CD22 molecules on the leukemia cell surface, but due to bryostatin-induced innate immune ligands that make the cells susceptible to CAR-T and UTD antigen non-specific killing." (PMID 35222407, 2022). "Although the leukemia cells no longer express the CD19 antigen, CD22 expression is usually retained." (PMID 38023730, 2023). "Combination therapy of bryostatin and CD22-CAR-T cells increases the CAR-T cell activity by increasing CD22 expression and sensitizing leukemia cells to CAR-T cell antigen-non-specific killing." (PMID 36248810, 2022).
B-cell lymphoma (64 papers, 2010 to 2026). "NCT03398967 and NCT03166878 (both at phase 1/2), designed to target CD19, CD20, and CD22 on B cells, are associated with B cell leukemia and B cell lymphoma immunotherapy." (PMID 36829496, 2023). "Most often, the CD22 internalization process was evaluated with one antibody on several B-cell lymphomas, underlining the variable internalization capabilities of cell lines of different origins." (PMID 32117707, 2020). "Although CD19 and CD22 chimeric antigen receptor (CAR-T) cell therapies have demonstrated encouraging clinical responses in patients with B-cell lymphoma, over 50% of patients ultimately experience disease progression due to frequent antigen escape." (PMID 41550973, 2026). "In a CD-22 directed CAR-T cell therapy a small Phase-I trial was conducted with 3 Large B-cell lymphoma patients who had relapsed CD-19 directed CAR-T therapy and were given at least 2 prior lines of therapy Large B-cell lymphomas showed complete remission." (PMID 41018125, 2025). "In another clinical trial involving CD19/CD22 bispecific CAR-T cells for R/R B-cell lymphoma, the response rate was 87.5%, with a CR rate of 62.5% and a partial response (PR) rate of 25%." (PMID 39844819, 2025). "Dual-targeted CAR T-cells, for example, targeting CD19 and CD22 for treating R/R aggressive B-cell lymphomas, are also in development." (PMID 39026972, 2024). "The first study of INO in humans was a phase I study in adults with relapsed or refractory CD22-positive B-cell non-Hodgkin’s lymphoma." (PMID 38734670, 2024). "CD22 is overexpressed in various B-cell lymphomas, such as CLL, ALL, and NHL, but it is expressed at low levels on immature B-cells and plasma cells." (PMID 35628495, 2022). "In conclusion, this clinical trial demonstrated promising efficacy and safety of CD19/CD22 CAR-T cocktail therapy for R/R aggressive B-cell lymphoma." (PMID 36552849, 2022). "Owing to the restricted expression on the B-cell and the inhibitory function of CD22, CD22 has been indicated as a therapeutic target in B-cell lymphoma." (PMID 35628495, 2022). "CD22 is another target explored in the treatment of B-cell lymphomas and leukemias in several ongoing clinical studies (i.e., NCT03999697, NCT04546906, NCT04088890)." (PMID 34203935, 2021). "CD20 is a commonly expressed mature B-cell antigen and is also expressed on a large proportion of B-cell lymphomas, whereas CD22 is an inhibitory co-receptor expressed on a range of mature B-cells, immature B-cells and B-cell lymphomas." (PMID 34680329, 2021). "For B-cell lymphoma only three genes are found in cosmic (CD22, MDN1, and PlCG2) and three genes (CD22, PTPN6, PLCG2) are oncogenes." (PMID 34570764, 2021). "CD19 and CD22 targeted therapy have been successful in the treatment of B cell lymphomas and rare Hairy Cell Leukemia (HCL), respectively." (PMID 32989604, 2020). "InO at 0.8 mg/m2 combined with full dose of rituximab, cyclophosphamide, vincristine, and prednisolone (R-CVP) was reported safe and effective for CD22+ R/R B cell NHL in a phase I trial (NCT01055496)." (PMID 31500657, 2019). "INO (CMC-544) was noted to inhibit the growth of CD22+ human B-cell lymphomas grafted subcutaneously into the mice in a dose dependent manner." (PMID 31011424, 2019). "InO at 0.8 mg/m2 plus full dose rituximab, gemcitabine, dexamethasone, and cisplatin (R-GDP) is a regimen proposed by another phase I trial (NCT01055496) for patients with R/R CD22+ B cell NHL." (PMID 31500657, 2019). "Preclinical Studies confirmed the potency and dose-dependent cytotoxicity of INO on CD22 positive B-lymphoma cell lines and anti-tumor efficacy in mouse models with B-cell lymphomas." (PMID 31011424, 2019). "In this work, we propose using DOX-loaded platelets that were conjugated with anti-CD22 antibodies (DOX–platelet–CD22) as a novel drug delivery system for the treatment of B-cell NHL." (PMID 28938559, 2017).
B-cell lymphoma (continued). "A phase 1 study of 79 patients with relapsed and refractory CD22+ B-cell NHL was conducted to determine the maximum tolerated dose, safety, and efficacy of INO." (PMID 26393619, 2015). "CD22 is a 135-kDa phosphoglycoprotein adhesion molecule present on the surface of B cells, including human B-cell lymphomas and leukemias." (PMID 22069564, 2010). "For targeting B-cell lymphoma cells, the anti CD22 monoclonal antibody RFB4 and the anti CD19 monoclonal antibody HD37 were conjugated to dgA." (PMID 22069564, 2010). "In a phase I clinical trial targeting CD19 and CD22 for the treatment of B-cell lymphoma, it was observed that the CD22 scFv triggered less cytokine secretion compared to the CD19 scFv, suggesting potential differences in the efficacy of CAR-T cells against different targets." (PMID 40072049, 2025). "Furthermore, CD22-TTC (BAY 1862864) has been investigated in a Phase 1 study in patients with CD22-positive relapsed/refractory B-cell non-Hodgkin lymphoma." (PMID 36726355, 2022). "Of the screened four genes (ALCAM, CD22, CASP1, and CISH), CD22 is a sialic acid-binding immunoglobulin-like lectin (Siglec) that is highly expressed on B cell lymphomas and is a validated target for antibody and nanoparticle-based therapeutics on non-Hodgkin lymphoma." (PMID 34026619, 2021). "Besides, there was another clinical trial that aimed at the efficacy and adverse events of CD19/CD22 CAR-T cell therapy for aggressive B-cell lymphoma involving gastrointestinal tract." (PMID 34256851, 2021). "Most engineered CAR-NK cells are directed against blood-related malignancies, such as CD19 for B cell lymphomas, CD22 for refractory B-cell lymphomas and solid tumors, NKG2D-ligand for pancreatic cancers, and CD33 and ROBO1 specific BiCAR-NK/T for malignant and metastatic solid tumors." (PMID 34925314, 2021). "These constructs specifically kill CD22-positive B-cell lymphoma cells in vitro." (PMID 30559744, 2018). "CD22 is also a promising target for antibody therapy since it is expressed by most B-cell NHLs." (PMID 26393619, 2015). "Given the clear preclinical activity in B-cell lymphoma models, INO was also tested in CD22-positive ALL models, where it induced complete tumor regression and cures in mice, warranting its clinical development in ALL." (PMID 38734670, 2024). "In a first-in-human dose-escalation phase I study, α-particle emitting 227Th-labeled anti-CD22 antibody (BAY 1862864) showed clinical safety and tolerability in patients with CD22-positive relapsed/refractory B-cell NHL." (PMID 38464386, 2024). "Recently, CD19/CD22 CAR-T cell therapy following ASCT showed a striking efficacy and manageable toxicity in a prospective study of aggressive B-cell lymphoma, including seven patients with tFL." (PMID 38246951, 2024). "Siglecs have long been associated with cancer: CD22 and CD33 are specific markers for B-cell lymphoma and anti-CD22 and anti-CD33 antibody therapies have also been used in clinical trials of B-cell lymphoma and myeloid leukemia." (PMID 37207210, 2023). "Current clinical trial studies of anti-CD22 CAR-NK cells (NCT03692767) and dual anti-CD19/CD22 CAR-NK cells (NCT03824964) are planned against relapsed and refractory B Cell lymphoma." (PMID 36612114, 2022). "In the present study, we aimed to evaluate the prognostic value of PET/CT-derived radiomic features for patients with B-cell lymphoma (BCL), who were treated with CD19/CD22 dual-targeted chimeric antigen receptor (CAR) T cells." (PMID 35198451, 2022). "Following CD19, targeting the antigens CD22 and CD20 represents two of the more promising strategies in clinical development for CAR-T therapies for B-cell lymphoma." (PMID 34680329, 2021). "Three early phase I clinical trials, in which recruiting has not yet started, will investigate the safety and efficacy of anti CD19 (NCT03824964), CD22, and CD19/CD22 (NCT03056339) CAR NK cells in patients with relapsed refractory B cell lymphoma." (PMID 31212634, 2019).
B-cell lymphoma (continued). "As a B cell lymphoma, MCL is characterized by the presence of characteristic B cell expression patterns with high (> 90%) expression of CD5, CD19, CD20, CD21, CD22, CD43, CD79a, sIg, and cIg, and low (< 10%) expression of CD10 and CD23." (PMID 27119356, 2016). "Inotuzumab ozogamicin (CMC-544), an anti-CD22-calicheamicin ADC, has been extensively studied in patients with both indolent and aggressive B-cell NHL as well as acute leukemias." (PMID 26605343, 2015). "Diffuse large B-cell lymphoma cells generally express pan B cell markers such as CD20, CD19, CD22, CD45 and CD79a; seventy percent of tumor cells express BCL-6 protein; CD10 is expressed in 30 to 60% of cases." (PMID 25294404, 2014). "One of the strengths of our WM scoring system is that it relies on antigen markers that are routinely used and widely available in haematology laboratories performing MFC analysis for B‐cell lymphomas (CD19, CD79b, CD22, FMC7 and CD27) and myeloid neoplasms (CD13)." (PMID 40407640, 2025). "The efficacy of such an approach has been confirmed in another study using murine models injected with a mixture of triple-positive cells, CD19-negative, CD20-negative, and CD22-negative B-cell lymphoma cell lines." (PMID 34203935, 2021). "For B‐cell NHL, the phase 1/2 NCT00299494 trial investigated the efficacy of INO plus rituximab for R/R CD20/CD22‐positive B‐cell NHL patients; the ORR was 87% and 74%, and the 2‐year PFS rates were 68% and 42% for follicular lymphoma (FL) and DLBCL, respectively." (PMID 34165267, 2021). "Due to the expression of CD22 not only on healthy but also malignant B-cells, CD22 is currently assessed as a target for CAR- and mAb-based immunotherapy approaches in the treatment of mainly ALL and B-cell lymphoma." (PMID 27689397, 2016). "CD22 is often used by practitioners of flow cytometry to define B-cells; however, CLL/SLL, follicular lymphoma and some large B-cell lymphomas can show low or very low expression of the antigen, and other B-cell lymphomas (such as hairy cell leukemia) show bright expression of CD22." (PMID 40075660, 2025). "In the murine models bearing a mixture of B-cell lymphoma lines composed of CD19 negative, CD20 negative, and CD22 negative variants, the trispecific duoCAR-T cells could efficiently kill tumor cells." (PMID 34256851, 2021). "However, as many CD19, CD20 and/or CD22 targeting CAR T cell products are currently under investigation and four different anti-CD19 CAR T cell products are already approved, the role of BCMA as target antigen for the treatment of B cell lymphoma is for now less clear compared to CD19." (PMID 38630291, 2024).